CST3 (cystatin C)
Diseases named in the same sentence as CST3 in open-access papers (continued):
Sharing a sentence is not in itself a finding about the gene and the disease.
atherosclerosis (continued). "The natural inhibitor of cysteine proteases, cystatin C, has been proposed to have a protective role in chronic inflammatory disorders such as RA and atherosclerosis." (PMID 21443774, 2011). "Structural changes in the glomerular basement membrane, as proposed in SGHS, may selectively impair filtration of medium‐sized proteins (5–30 kDa), including cystatin C, and potentially atherosclerosis‐promoting proteins." (PMID 41273211, 2026). "However, recent studies have shown that cystatin C plays a unique role in disease states such as atherosclerosis and cancer." (PMID 40933994, 2025). "Emerging evidence suggests that cystatin C may be involved in extrarenal pathologies, including subclinical atherosclerosis, endothelial dysfunction, and neuroinflammatory cascades." (PMID 40941489, 2025). "Similarly, higher levels of homocysteine and cystatin C can lead to atherosclerosis and thrombosis by damaging vascular endothelial cells and affecting lipid metabolism." (PMID 37934082, 2023). "Subsequent researches reported that atherosclerosis relevant inflammatory cells and cytokines could stimulate the production of lysosomal cathepsins, and lead to the increased the plasma cystatin C concentrations." (PMID 37817071, 2023). "Measurement of the levels of cystatin C may characterize this imbalance and provide insight into the severity and prognosis of atherosclerosis." (PMID 35883416, 2022). "Further research is warranted to assess whether reducing the risk factors of increased serum cystatin C favorably affected serum cystatin C levels and subclinical atherosclerosis development." (PMID 33129312, 2020). "However, the odds ratios of the serum cystatin C level for other systemic atherosclerosis indexes, including the baPWV (ORs = 1.13, P = 0.6317) and the max IMT (ORs = 1.09, P = 0.7657), were not significant." (PMID 29513723, 2018). "Cst C has been implicated in a number of conditions including apoptosis, antigen presentation, atherosclerosis and pathogen invasion, and the level of Cst3 mRNA can be influenced by different stimuli like inflammatory cytokines, pathogens, growth factors, hormones and oxidative stress." (PMID 28495919, 2017). "An imbalance between cysteine proteases and their inhibitor, cystatin C, may affect vascular inflammation, potentially leading to the development of atherosclerosis and inflammatory disorders." (PMID 28922364, 2017). "High serum cystatin C was thought to be related directly to both inflammation and atherosclerosis." (PMID 26402227, 2015). "With these results, we suggested that cystatin C could be used as a marker in clinical practice to predict the presence of severity of atherosclerosis in suspected CAD patients." (PMID 24478035, 2014). "asymptomatic CAD is that cystatin C is associated with inflammation regardless of renal function Inflammation is a critical step in the development of atherosclerosis." (PMID 22978689, 2012). "Cystatin C also has a different role in relation to inflammation/atherosclerosis." (PMID 22152087, 2011). "Studies have shown that both cathepsins and their inhibitor cystatin C could act either pro- or antiatherogenic in the different stages of atherosclerosis." (PMID 22152087, 2011). "Thus, cystatin C is a potential biochemical marker for early diagnosis of atherosclerosis." (PMID 37273348, 2023). "Indeed, it is demonstrated that by modulating the activities of cysteine proteases, CST3 is shown to play an important role in the pathology of several disease processes including atherosclerosis, tumor metastasis, chronic kidney diseases and inflammatory conditions." (PMID 32170118, 2020). "Hence, white matter disturbance in the subject group might not be caused by atherosclerosis, rather directly affected by CST3-mediated alteration of protease activities." (PMID 32170118, 2020).
atherosclerosis (continued). "Therefore, the underlying mechanisms by which non-GFR determinants of cystatin C affect cardiovascular outcomes may be as follows: first, cystatin C may induce inflammation and promote the progression of atherosclerosis." (PMID 31317040, 2019). "Therefore, assessment of serum cystatin C may allow early detection of atherosclerosis." (PMID 28922364, 2017). "Cell types potentially involved in the release of EV-cystatin C and EV-CD14 include activated monocytes, endothelial cells and platelets, which are all present in high numbers in atherosclerosis lesions." (PMID 24498934, 2014). "In previous studies, cystatin C levels in RA patients were positively correlated with clinical and laboratory measures of inflammation, but not independently with atherosclerosis in RA." (PMID 37899440, 2023). "This study supports the hypothesis, and its clinical implications, that cystatin C elevation, related to EAT accumulation, exerts an additional impact on atherosclerosis development." (PMID 28922364, 2017).
coronary artery disease (51 papers, 2009 to 2025). "Another study showed an association between a genetically determined decrease in cystatin C expression and increased severity of coronary artery disease." (PMID 35308546, 2022). "Circulating cystatin C (cys-C/CYC) has been identified as an independent predictor of all-cause mortality in patients with coronary artery disease and the general population." (PMID 30643006, 2019). "A Chinese study found that increased circulating ADMA concentrations were associated with elevated circulating cystatin C concentrations in patients with coronary artery disease." (PMID 27893762, 2016). "In conclusion, the present study is the first to demonstrate an association between elevated serum cystatin C and reduced angiographic coronary collateralization in a large cohort of stable coronary disease patients with chronic total occlusion." (PMID 26402227, 2015). "Serum cystatin C reflects angiographic coronary collateralization in patients with stable coronary artery disease, and cystatin C ≥ 0.97 mg/L indicates a great risk of poor coronary collaterals." (PMID 26402227, 2015). "This study showed that elevated serum cystatin C was associated with poor coronary collateralization in patients with stable coronary artery disease and chronic total occlusion." (PMID 26402227, 2015). "For example, in patients with ischemic heart disease, cystatin-C was found to be an independent risk factor together with traditional cardiovascular risk factors, renal function, or the presence of microalbuminuria." (PMID 23240006, 2012). "These genes included Cdh13 and Lpl from Cluster 1; Nfia, Col4a1 and Serpinh1 from Cluster 2; Arhgef12, Col4a2, Scarb1 and Cst3 from Cluster 3; Pecam1 and Aldh2 from Cluster 4, providing plausible molecular basis for the inextricable causal link between age and coronary artery disease." (PMID 35615560, 2022). "We investigated whether and to what extent cystatin C was associated with angiographic coronary collateralization in patients with stable coronary artery disease and chronic total occlusion." (PMID 26402227, 2015). "The aim of our study was to assess whether there is a causal relationship between plasma concentration of cystatin C and risk of coronary artery disease (CAD) using a Mendelian Randomization approach." (PMID 26057752, 2015). "Furthermore, a meta-analysis revealed that serum cystatin C is independently associated with adverse vascular outcomes in participants with suspected or established coronary artery disease in terms of all-cause and cardiovascular mortalities, independent of creatinine-based eGFR." (PMID 40983592, 2025). "However, significantly reduced serum cystatin C levels, which had been correlated with variant haplotypes, were highlighted in association with atherosclerotic lesions, dilated aorta and focal progression of coronary artery disease." (PMID 32049341, 2020). "NT-pro BNP, MR-proADM, cystatin C, and CRP were all independently associated with the occurrence of symptomatic CAS, in addition to their previously documented associations with coronary artery disease and congestive heart failure." (PMID 39062558, 2024). "In some studies, polyvascular atherosclerotic manifestations, as coexisting PAD and CAD (coronary artery disease), showed significantly higher cystatin C values than PAD or CAD alone." (PMID 35453881, 2022). "After adjusting for age, gender, risk factors for coronary artery disease, GFR and hsCRP, serum cystatin C ≥ 0.97 mg/L remained independently associated with poor collateralization (OR 2.374, 95% CI 1.660 ~ 3.396, P < 0.001)." (PMID 26402227, 2015). "Cystatin C levels could independently predict fasting plasma homocysteine levels among stable coronary heart disease participants with normal serum creatinine levels." (PMID 37587534, 2023).
coronary artery disease (continued). "Similarly, increased levels of cystatin-C, a marker of renal function, in Asians and their overall and ischemic heart disease deaths, and glucose in Whites dying from digestive cancers, were significantly increased the risk of mortality." (PMID 36963080, 2023). "As an endogenous inhibitor cystatin C, promising biomarkers in the diagnosis of coronary artery disease, it may favor proteolysis of extracellular matrix (ECM) in the pathogenesis of ASCVD by participating in inflammation and extracellular matrix remodeling." (PMID 36114495, 2022). "Moreover, cystatin C has a shorter half-life and provided an early prediction of kidney dysfunction in coronary heart diseases in spite of a normal serum creatinine level." (PMID 36466932, 2022). "The researchers highlight that feasibility studies looking at cathepsins as diagnostic tools have shown promising results in the use of cathepsins S and L, and the endogenous inhibitor cystatin C as biomarkers for determining coronary artery disease and the formation of aneurysms." (PMID 29379789, 2017). "In this study, we hypothesized that elevated cystatin C level is an indicator of poor coronary collateralization in patients with stable coronary artery disease." (PMID 26402227, 2015). "Cystatin C, an endogenous anti-angiogenic factor, was considered as an emerging biomarker in cardiovascular disease and proved to be an important predictor for adverse outcomes among patients with coronary artery disease." (PMID 26402227, 2015). "In addition, we investigated whether cystatin C can serve as a biomarker to predict the presence of multivessel coronary artery disease." (PMID 32306911, 2020). "Cystatin C emerged as a potential marker for identifying multivessel disease in populations that may benefit from therapeutic strategies aimed at preventing the development of multivessel coronary artery disease." (PMID 32306911, 2020). "The aim of this study was to investigate the role of cystatin C level as a predictor of cardiovascular events in patients with coronary artery disease (CAD)." (PMID 24478035, 2014). "The prevalence of coronary artery disease, cerebral infarction and LLI increased with cystatin C (P<0.01), and the prevalence of LLI in patients with cystatin C >1.2 mg/L was much higher than other three quartile groups." (PMID 23843968, 2013). "Therefore, the detection of serum cystatin C concentrations is helpful for the early diagnosis of CHD, especially for the severity and prognosis of coronary artery disease." (PMID 37663661, 2023). "Cystatin C has been found to be closely related to T2DM and coronary heart disease." (PMID 34007274, 2021). "Examining the larger cohort of 308 participants with PET imaging, participants with vs. without cystatin C measurement (166 vs. 142 participants) differed only on coronary artery disease (9 vs. 18%, p = 0.02; data not shown)." (PMID 34616751, 2021). "Cystatin C was a strong independent predictor for mortality (p < 0.001) and additionally, S-AKI and the coexistence of ischemic heart diseases were also accepted by the Cox regression model as independent predictors of mortality (p < 0.001, 0.029 respectively)." (PMID 34692772, 2021). "The use of 3 biomarkers – cystatin-C (Cys-C), retinol-binding protein (RBP), and ischemia-modified albumin (IMA) – for the clinical classification and outcome of coronary heart disease (CHD) has not been adequately evaluated." (PMID 39213212, 2024).
diabetic nephropathy (47 papers, 2010 to 2026). "This study evaluated the diagnostic performance of Cystatin C in the early detection of diabetic kidney disease (DKD)." (PMID 39502964, 2024). "Increased cystatin C and disorders of lipid metabolism are associated with diabetic nephropathy in T2DM patients." (PMID 37082121, 2023). "The resulting data showed that cystatin C has a greater causal association with diabetic nephropathy (IVW OR: 1.36, 95%CI [1.15, 1.61], p=0.0004), and Cochran’s Q-test no longer showed evidence of heterogeneity (IVW p>0.05)." (PMID 36482996, 2022). "Among 6 serum biomarkers, only cystatin C has a significant causal effect on diabetic nephropathy as a risk factor (IVW OR: 1.19, 95%CI [1.04, 1.35], p=0.009)." (PMID 36482996, 2022). "Serum cystatin C has an excellent diagnostic value with good sensitivity and specificity for diabetic nephropathy." (PMID 35655297, 2022). "Among the six serum biomarkers, only cystatin C causally associated with diabetic nephropathy (IVW OR: 1.36, 95%CI [1.15, 1.61])." (PMID 36482996, 2022). "This prospective study was conducted to assess the diagnostic accuracy of serum cystatin C in detecting diabetic nephropathy at earlier stages." (PMID 33996155, 2021). "We constructed a nomogram which contained hemoglobin, NLR, serum cystatin C, eGFR, and 24-h urine protein to predict the risk of patients with diabetic kidney disease initiating renal replacement in 3 years." (PMID 32524865, 2020). "Previous studies have supported the diagnostic value of cystatin C in diabetic nephropathy." (PMID 41517402, 2025). "Among these proteins, increased levels of mannose-binding protein C (Mbl2), cystatin C (Cst3), and proto-oncogene vav (Vav1) might increase the risk of diabetic nephropathy." (PMID 36335368, 2022). "Two-step MR results indicated that BMI might mediate the causal effect of cystatin C on diabetic nephropathy." (PMID 36482996, 2022). "Hence, the risk of diabetic nephropathy would increase by 19% with per SD increase of cystatin C. Cochran’s Q test of cystatin C indicates that there is evidence of heterogeneity (IVW p<0.05), while no indication of pleiotropy in MR-Egger (p for intercept>0.05)." (PMID 36482996, 2022). "However, the causal relation between cystatin C and diabetic nephropathy remains uncertain." (PMID 36482996, 2022). "Therefore, cystatin C might be useful to detect patients with incipient diabetic kidney disease that present an increased risk of cardiovascular disease, contributing to an early adoption of reno and cardioprotective therapies." (PMID 29694626, 2018). "Thus, the diagnostic biomarkers that are able to recognize early diabetic kidney disease include the decreased (e) creatinine clearance, or glomerular filtration rate, the increased fractional excretion of magnesium (FE Mg) and the decreased cystatin C." (PMID 28494191, 2017). "They concluded that cystatin C offers greater sensitivity and specificity when detecting early diabetic nephropathy compared with these traditional markers." (PMID 41517402, 2025). "Increasing serum cystatin C levels by one unit was associated with 1.41 times (AOR: 1.41, 95% CI: 1.09, 2.77) higher odds of having diabetic nephropathy." (PMID 37082121, 2023). "This study aimed to evaluate serum cystatin C and lipid profiles for assessing the potential predictor markers of diabetic nephropathy in patients with T2DM." (PMID 37082121, 2023). "Plasma potential biomarkers such as apolipoprotein C-I, apoA-I, transthyretin, and cystatin C were purposed to predict the progression and response to the treatment in diabetic kidney disease." (PMID 36865924, 2023). "Next, we performed multivariable MR to further analyze the direct effect of cystatin C on diabetic nephropathy." (PMID 36482996, 2022). "To assess the precise prognostic value of cystatin C, we need further follow-up studies of these young T1D patients to identify those who will develop advanced diabetic kidney disease." (PMID 35208542, 2022).